TBK1 (TANK binding kinase 1)
Diseases named in the same sentence as TBK1 in open-access papers (continued):
Sharing a sentence is not in itself a finding about the gene and the disease.
viral infection (continued). "We identify TFG as being part of a molecular complex comprised of at least MAVS, TRAF3 and TBK1 and requirement of TFG in the interactions of TRAF3 with TBK1 and MAVS upon viral infection." (PMID 33411856, 2021). "We also show for the first time that Bmp8a interacts with Alk6a, which promotes the phosphorylation of Tbk1 and Irf3 through p38 MAPK pathway, and induces the production of type I interferons (IFNs) in response to viral infection." (PMID 33750893, 2021). "Following viral infection, a protein named recombinant TANK binding kinase 1 (TBK1) sends a signal that induces a protective program to inhibit viral replication." (PMID 34061266, 2021). "TANK-binding kinase 1 (TBK1)/IκB kinase-ε (IKKε) mediates robust production of type I interferons (IFN-I) and proinflammatory cytokines in response to acute viral infection." (PMID 34908452, 2021). "TANK-binding kinase 1 (TBK1) is a crucial factor that mediates the activation of IRF3, leading to the induction of IFN-α/β following viral infections." (PMID 34646390, 2021). "Upon virus infection, IRF3 is phosphorylated at its C-terminus by TBK1 and IκB kinase ε, and is translocated into the nucleus as a dimer." (PMID 33801464, 2021). "This special modification of TBK1 inhibits its phosphorylation at Ser172, hence regulating the release of IFN-I in the process of virus infection." (PMID 34966372, 2021). "TANK-binding kinase 1 (TBK1) has been reported to be in the upstream of both the IRF7 pathway and the NF-kB pathway in virus infection." (PMID 31941042, 2020). "Viral infection upregulates the expression of TRIM21, thereby promoting the recruitment of TBK1 to MAVS and enhancing downstream signaling." (PMID 32536927, 2020). "TRIF has been shown to form a complex with TBK-1, a protein kinase that has been reported to directly phosphorylate IRF-3 and IRF-7 in response to viral infection or TLR3 and TLR4 stimulation based on in vitro kinase assays." (PMID 32373120, 2020). "Consistent with the cytokine levels, the knockdown of β-arrestin 2 significantly reduced the phosphorylation of TBK1, IRF3, IRF7, and STING and also the dimerization of IRF3 during virus infection." (PMID 33243993, 2020). "HSV-1 VP24 protein binds IRF3 to prevent TBK1/IRF3 interaction and block the phosphorylation and dimerization of IRF3 during viral infection." (PMID 33391252, 2020). "It is very well studied that TANK-binding kinase 1 (TBK1) and IƙB kinase ɛ (IKKɛ) regulate the production of type 1 interferons (IFNs), which trigger antiviral responses during viral infections." (PMID 32967676, 2020). "THOC7 interacted with MAVS, TBK1, IKKε, and IRF3 and, notably, the interaction was decreased with MAVS, but increased with TBK1 after virus infection, indicating that THOC7 have a significant function by targeting TBK1 in the antiviral response." (PMID 30769920, 2019). "The TBK1, a downstream transcription factor of IPS-1, mediates the activation of IRF3, leading to the induction of IFN-I following viral infections, and is also tightly regulated to effectively control viral infections and maintain immune homeostasis." (PMID 31330869, 2019). "The phosphorylated TBK1 further activates IRF3 and induces the phosphorylated IRF3 to translocate into nuclei, and then it induced the secretion of cytokines IFN-β against viral infection." (PMID 31975996, 2019). "Mammalian TBK1 is constitutively expressed and unchanged during viral infection, but expression of fish TBK1 can be induced by stimulation of various viral/bacterial PAMPs (PMA, poly I:C, β-glucan, and LPS) and viral infection (SVCV and GCRV)." (PMID 29441066, 2018). "Overexpression of TBK1_tv1 and TBK1_tv2 inhibits RIG-I-, MAVS-, TBK1-, and IRF3-mediated activation of IFN promoters in response to spring viremia of carp virus infection." (PMID 29441066, 2018). "We found that TBK1 and IKKε were recruited to MAVS only in TRAF6-expressing cells upon viral infection." (PMID 29125880, 2017).
viral infection (continued). "It indicates that FBXW7 regulates RIG-I signalling through SHP2/RIG-I instead of SHP2/TBK1, as the interaction between SHP2 and RIG-I was enhanced and predominant during virus infection." (PMID 28287082, 2017). "Although it has been well studied how RLRs recruit and activate MAVS upon virus infection, it remains to be elucidated how MAVS activates its downstream components, including kinases TBK1/IKKε and the IKK complex." (PMID 29125880, 2017). "Instead, Gsk3β mediates oligomerization and auto-phosphorylation of TBK1, a kinase responsible for IRF3 phosphorylation after viral infection." (PMID 28754897, 2017). "Recent studies have revealed that STING acts as a scaffold protein for TBK-1 and IRF3 and links them to the MAVS complex in mitochondria upon viral infection." (PMID 29201911, 2017). "Following sensing of viral infection by RIG-I/MDA5 and activation of MAVS, TBK1 is activated which leads to the phosphorylation of the interferon regulatory factor 3 (IRF3)." (PMID 28883463, 2017). "Activation of TBK1 leads to adaptor phosphorylation, IRF3 activation and expression of IRF3-dependent genes that are important for the response to viral infection; thus, their activities are tightly regulated." (PMID 28591144, 2017). "Mechanistically, GPATCH3 was recruited to VISA in a viral infection dependent manner and the assembly of VISA/TRAF6/TBK1 signalosome was impaired in GPATCH3-overexpressing cells." (PMID 28414768, 2017). "TBK1 is a critical adaptor molecule that is involved in the TLRs, RLRs and STING signaling pathways that induce type I IFN production after virus infection in mammals." (PMID 28493975, 2017). "Post-translational modifications of some lysine residues of TBK1 through the addition of K63-linked polyubiquitin chains have been shown to be required for TBK1 activation and type I IFN production after viral infections." (PMID 27538435, 2016). "Upon viral infection, recognition of viral RNA by RIG-I induced a downstream signaling cascade, including MAVS, TBK1, IRF3." (PMID 27213432, 2016). "Upon viral infection, a subcellular fraction of SNRNP200 relocalizes with TBK1 into perinuclear cytoplasmic speckles." (PMID 27454487, 2016). "Release of the CYLD-mediated inhibition of TBK1 during this phase results in enhanced IFN/ISG signaling pathway, independently of viral infection." (PMID 25923723, 2015). "Although the IPS-1 interaction with TRAF6 provides another link to IKKαβ, the linkage of RIG-I or RIP-1 to TBK1 and NF-κB for production of pro-inflammatory cytokines and anti-viral IFN-β is unclear in viral infections." (PMID 25754842, 2015). "IFNβ-containing culture media were obtained from 293T cells transfected with a RIG-I signaling component (MAVS or TBK1) and TRIM11 or empty vector, and then used to treat Vero cells prior to viral infection with HSV-1 or VSV-GFP." (PMID 23675467, 2013). "TBK-1 was previously identified as a kinase that phosphorylates the carboxyl terminus of the related transcription factor, IRF3, in response to viral infection." (PMID 22412986, 2012). "Reciprocally, mild overexpression of Sec16A or p115 in Hec1B cells increased the activation of IFNβ, ISG56 and NF-κB -dependent promoters following viral infection and ectopic expression of MAVS and Tank-binding kinase-1 (TBK1)." (PMID 22792062, 2012). "Using RNA based microarray assay, overall changes at the transcription level were illustrated by intensity in response to virus infection or poly (I:C) simulation, and it was found that TBK1-TANK binding contributed greatly to the TBK1 activation." (PMID 23162545, 2012). "It has been previously demonstrated that the two non-canonical IκB kinase homologs, namely IκB kinase-ε (IKK-ε or IKKi) and TANK-binding kinase-1 (TBK1), are involved in the C-terminal phosphorylation of IRF3 upon dsRNA stimulation or viral infection." (PMID 21347389, 2011).
viral infection (continued). "TRAF3 is a critical signalling molecule for IFNβ activation in response to virus infection, and is a well established binding partner for the TBK1 adaptor protein TANK, residing in a trimeric complex containing TBK1." (PMID 20174559, 2010). "We and others have previously demonstrated that IKK-related kinases, IKKε and TBK1, are part of the kinase activity that is essential for IRF-3 phosphorylation and subsequent activation of IRF-3 in the context of virus infection." (PMID 20532218, 2010). "The present results suggest a biphasic regulation or “immune-editing”, whereby TRAF3 is Lys63 polyubiquitinated early after virus infection to bridge protein-protein interactions between MAVS and TBK1/IKKε." (PMID 19893624, 2009). "As a control, C156-P1 treatment alone, without virus infection, did not change the levels of phosphorylated TBK1 and IRF3." (PMID 41004242, 2025). "While our data demonstrate that the LIT domain is specifically required for ALTO-mediated TBK1 activation, it remains to be determined whether LIT can also modulate TBK1 phosphorylation in response to other upstream stimuli such as poly I/C or viral infection." (PMID 41277846, 2025). "We further found that under virus infection conditions, endogenous GSDMD‐CT, cleaved from GSDMD, could interact strongly with RIG‐I and TBK1." (PMID 40539222, 2025). "Its expression undergoes significant upregulation following viral infection or immune stimulation, mediated through critical signaling pathways IFN(Interferon), NF-κB(Nuclear Factor kappa B), TBK-1(TANK-Binding Kinase 1), and IKK-ɛ(Inhibitor of Nuclear Factor Kappa-B Kinase Subunit ɛ)." (PMID 40980176, 2025). "What calls for special attention is that bat TBK1 constitutively enhances the IRF3-mediated interferon pathway under basal conditions (in the absence of viral infection)." (PMID 40791583, 2025). "In DFO-treated PMs, FPN1 deficiency had no inhibitory effect on viral infection-induced cytokine expression or the phosphorylation of IRF3 and TBK1." (PMID 40595467, 2025). "However, DMF pretreatment significantly inhibited both GSDME cleavage and TBK1 phosphorylation, highlighting the role of GSDME cleavage in TBK1 activation during viral infection." (PMID 41550948, 2025). "Consequently, viral infection contributes to an increase in cellular iron accumulation; in turn, ferrous iron attenuates type I IFN responses and autophagy by promoting TBK1 hydroxylation and STING carbonylation." (PMID 40595467, 2025). "Because the suppression of viral replication by ALTO is known to occur through a TBK1-driven negative feedback mechanism, this loss of function demonstrates that the LIT domain is required for TBK1 stimulation by ALTO during viral infection." (PMID 41277846, 2025). "These targets include STAT3, which is a key regulator of the host's innate response to viral infections, IFNAR1, a vital antiviral factor, MDA5, an RNA antiviral sensor, and protein kinase TBK1, which participates in the induction of type I interferons in response to viral replication." (PMID 38501860, 2024). "Additionally, increased level of signaling molecules IRF-3 and TBK1 observed in the Berb-treated group indicate activation of the IRF-3-TBK-1 pathway, enhancing the expression of IFN-β, IFITM, and OAS1g, which are crucial in combating viral infections." (PMID 39640591, 2024). "Subsequently, the TBK1-mediated IRF3 axis or the IKKs-mediated NF-κB axis is employed, resulting in the production of IFN-I, pro-inflammatory cytokines, and chemokines in response to viral infection." (PMID 39058724, 2024). "Ikki−/−Tbk1−/− MEFs did not exhibit any phosphorylated AIP band shifts after virus infection, indicating a requirement for TBK1/IKKi in phosphorylating AIP following RNA virus infection." (PMID 38043800, 2023). "Next, we measured TBK1 ubiquitination in PMs after different PAMP pretreatments following viral infection and found that the overall ubiquitination level was not affected." (PMID 37243289, 2023).
viral infection (continued). "Based on the observation from this recent study, we aimed at further investigating the consequences of TBK1 deletion for antiviral defense of human monocytic cells, essential players in innate immune recognition and important inducers of type I IFN upon viral infection." (PMID 36936901, 2023). "After detecting viral DNA or RNA, IFI16 induces the STING-dependent signal transduction through the TBK1-mediated IRF3 axis or IKKs-mediated NF-κB axis, which results in the production of IFN-I, proinflammatory cytokines, and chemokines against viral infection." (PMID 37410794, 2023). "In this study, we found that the interaction of NSs to TBK1 results in the inhibition of the IFN-I induction by viral infection, regardless of the cell type." (PMID 37187292, 2023). "STING has been studied as a negative host factor for viral infections since it is a key component of the cGAS/STING/TBK1/IRF3 regulatory axis activating interferon pathway, and therefore as a target of viral immune evasion." (PMID 36455047, 2022). "Synthesized 2′,3′-cGAMP interacts with ER-resident STING and triggers downstream signaling of type I IFNs through TBK1 and IKK, inducing the activation of IRF3 and releasing cytokines, including type I IFNs, the first line of defense against viral infections (50, –, 55)." (PMID 35861515, 2022). "In addition, DDOST knockdown impaired gradient viral infection (multiplicity of infection (MOI) = 1, 2, 4)-induced phosphorylation of TBK1 and IRF3." (PMID 36449507, 2022). "Importantly, we detect interaction of TRIM18 with both PPM1A and TBK1 after virus infection, which drove us to further investigate the molecular mechanisms by which TRIM18 targets TBK1 to dampen type I IFN production in virus infection." (PMID 35909127, 2022). "Upon viral infection, IRF3 in the cytoplasm of the infected cells is phosphorylated by the kinases TBK1 and IKKε, and undergoes a conformational change and homo-dimerization, which permits its translocation to the nucleus where it binds the ISRE of target genes." (PMID 36082118, 2022). "The steady state mRNA levels of Tbk1 and Irf3 in both Mettl14+/+ and Mettl14+/− macrophages were not changed after virus infection." (PMID 34047074, 2021). "Similarly, MAVS and TBK1 induce the constitutive expression of IFN and ISGs, conferring on fish cells protection against virus infection." (PMID 33600488, 2021). "Upon viral infection, together with TBK1, TRAF3 transits from the perinuclear region onto MAVS-containing supramolecular complexes and promotes signaling events leading to TBK1 activation." (PMID 33411856, 2021). "Upon virus infection, the upregulation of phosphorylated TBK1 was observed, whereas with the expression of CARDs, the phosphorylated IRF3 and further upregulation of phosphorylated TBK1 were obvious." (PMID 34177861, 2021). "The levels of p-IRAK4, p-TAK1, and p-TBK1 were activated by SeV, but repressed by Sox4, indicating that Sox4 attenuates both TLR/MyD88/IRAK4/TAK1 and TLR/TRIF/TRAF3/TBK1 pathways in response to viral infections." (PMID 33517839, 2021). "TBK1 and IRF3 are the key effectors during viral infections to induce IFN production." (PMID 32486349, 2020). "Many picornaviruses hijack autophagic pathways to generate sites for viral RNA replication and to facilitate non-lytic release of virions Possibly, cleavage of TBK1 by Lpro facilitates the use of autophagy to aid viral infection and propagation." (PMID 32667958, 2020). "In the infected cells, TLR3 can recognize dsRNA and activate TBK1 by acting on the TRIF-dependent pathway; then, phosphorylated IRF3 is induced to translocate into nuclei; finally, it can induce the secretion of cytokines IFN-β against viral infection." (PMID 31975996, 2019). "Additionally, we examined the effect in the presence and absence of THOC7 in MCF7 cells and found a weak downregulation of TBK1 by THOC7 expression, but obvious effect upon virus infection." (PMID 30769920, 2019).
viral infection (continued). "Originally characterized as an endogenous inhibitor of TBK1 when overexpressed in viral infection and pathological cardiac hypertrophic models, a mechanistic study revealed that SIKE acts as a high‐affinity substrate of TBK1, but its function remains unknown." (PMID 29988566, 2018). "Of particular interest is DDX3X, a crucial regulator of the TBK1/IRF3 signaling leading to induction of IFN-β31,32, which may potentially modulate airway epithelial innate responses against viral infections." (PMID 29615635, 2018). "Taken together, our results identified ERRα as an important negative downstream regulator of TBK1 in RLRs-TLRs signaling pathways and suggested a potential therapeutic target for viral infection." (PMID 28591144, 2017). "Viral infection also leads to activation of RIG-I and TBK-1/IKKε signaling pathway." (PMID 28589097, 2017). "TBK1 plays an indispensable role in IFN induction because the activation of IRF3 and IFNβ is impaired in TBK1-defective (not IKKε-defective) murine fibroblasts after virus infection." (PMID 28493975, 2017). "Recently, the adaptor protein endoplasmic reticulum IFN stimulator (STING, also known as MITA/ERIS), along with MAVS and TBK1, were identified for their contribution to STAT6 activation during viral infection with Semiliki Forest virus and herpes simplex virus 1 (HSV-1)." (PMID 27143388, 2016). "Upon viral infection, IRF3 is phosphorylated and activated by active TBK1 or IKKε." (PMID 26811330, 2016). "In summary, it has been demonstrated that upon virus infection, the SNRNP200 RNA helicase in combination with TBK1 via its Sec63-1 domain recognizes viral RNA, relocalizes into TBK1-containing cytoplasmic structures, and positively regulates IRF3 phosphorylation to promote the antiviral response." (PMID 27454487, 2016). "A previous study has shown that cells lacking IRF3 are unable to produce type I IFN in viral infections and that TBK1 and IKK-I control both IRF3 and STAT1." (PMID 25942440, 2015). "Several phosphatases have been identified as regulators of TBK1 phosphorylation, including the inositol 5’ phosphatase SHIP-1 or protein phosphatase Mg2+/Mn2+ dependent 1B (PPM1B/PP2Cβ), during TLR3 stimulation or virus infection, respectively." (PMID 25923723, 2015). "Upon viral infection, MITA translocates to intracellular membrane-containing compartments to form punctate aggregates and acts as a scaffold protein to facilitate the phosphorylation of IRF3 and STAT6 by the kinases TBK1 and IKKε." (PMID 25254379, 2014). "However, TRAF3 was demonstrated to link the mitochondrial membrane-bound protein MAVS to the activation of TBK1, which is required for IRF3/7 phosphorylation and type I IFN induction in response to viral infection." (PMID 22792062, 2012). "By 6 hr post infection, both Ku80 and DNA-PKcs had accumulated in these viral factories together with the IRF-3-activating kinase TBK1, consistent with its role in this sensing pathway, although IRF-3 was mostly nuclear, reflecting its activation by virus infection." (PMID 23251783, 2012). "Once activated, TRAF3 and TRAF6 induce the activation of TANK-binding kinase 1 (TBK1), IKK, and MAPKs, which in turn activate the transcription factors IRF3, NF-κΒ, and activating protein 1 (AP-1), thereby initiating a rapid antiviral response to defend against various types of viral infection." (PMID 40495154, 2025). "Here the authors show that viral infections facilitate accumulation of cellular iron by degradation of iron exporter ferroportin (FPN1), and that high intracellular iron suppresses type I IFN responses and autophagy by promoting TBK1 hydroxylation and STING carbonylation." (PMID 40595467, 2025). "Virus infection is detected by pattern recognition receptors (PRRs), including various types of Toll-like receptors (TLRs) and activates IRFs by phosphorylation through IRF kinases, such as TANK-binding kinase 1 (TBK1), transforming growth factor beta-activated kinase 1 (TAK1) and IKKε." (PMID 41153438, 2025).